EGFR (epidermal growth factor receptor)
Diseases named in the same sentence as EGFR in open-access papers (continued):
Sharing a sentence is not in itself a finding about the gene and the disease.
cancer (continued). "Therefore, it could be inferred that cub isoform functions during cancer initiation in EGFR signalling." (PMID 36452073, 2022). "In EGFR-mutated cancers, TME displays high Treg infiltration without CD8+ T-cell infiltration." (PMID 35742933, 2022). "Silencing of EGFR via anti-EGFR siRNA could be an effective strategy for cancer management." (PMID 36412852, 2022). "In addition, B-ASO may have a dual effect: on the one hand, they provide a therapeutic platform for BNCT, and on the other hand, they reduce the mRNA of EGFR by antisense activity, thus decreasing the radio-resistance of cancer cells." (PMID 36293047, 2022). "The proliferation is primarily attributed to kinases known as EGFR-TK (Epidermal Growth Factor Receptor-Tyrosine Kinase), which form part of the family of tyrosine kinases, and are currently considered an important target in the design and development of the new anti-cancer agents." (PMID 35742992, 2022). "Thus, a novel genetically-engineered protein, MGL S3, could be used for the precise targeting of EGFR-dependent cancer cells, and combined with EGFR inhibitors." (PMID 36361596, 2022). "Therefore, several antibodies for EGFR have been developed and approved for cancer treatment, such as cetuximab (CTX), nimotuzumab, panitumumab, and necitumumab, and many nanoparticle formulations have been functionalized with these antibodies with the aim of better targeting." (PMID 36559202, 2022). "Based on the phenomenon that EGFR-TKIs induce autophagy, and autophagy may lead to chemotherapy resistance, researchers speculate that autophagy may be a protective mechanism for cancer cells and contribute to the emergence of drug resistance in NSCLC." (PMID 35600411, 2022). "Given the known role of the EGFR in pathologies such as cancer and auto-immune diseases, the physiological and translational significance of our findings is that they provide new insights into how the processing and functional activation of EGFR-ligands by ADAM17 may be regulated." (PMID 36361585, 2022). "Therefore, 1,25(OH)2D3 may play an important role in the regulation of EGFR-TKI resistance in NSCLC cells and the mechanism may be closely associated with its regulation of cancer stem-like properties." (PMID 35301287, 2022). "Our results provide novel insights into the probable mechanism through which USP6NL/EGFR signaling might suppress the anticancer therapeutic response, induce cancer invasiveness, and facilitate reduced sensitivity to temozolomide treatment in GBM in an autolysosome-dependent manner." (PMID 35884836, 2022). "It was reported that lovastatin inhibited EGF-induced EGFR autophosphorylation and its downstream signaling, and the combined treatment of gefitinib with lovastatin induced synergistic anti-proliferative and pro-apoptotic effects in cancer cell lines, including NSCLC cells." (PMID 35159223, 2022). "Thus, it can be anticipated that during DCIS, grade 2 and grade 3, the isoform switches from canonical to cub isoform where the cells need to proliferate cancer growth via EGFR signalling pathway and the pathway is upregulated by the indirect activation of TACE by GPCR agonists." (PMID 36452073, 2022). "However, combining radiation for EGFR and Bcl-2 obstruction may be a new plan for targeting cancer stem cells." (PMID 35402265, 2022). "Therefore, EGFR-targeting therapy remains the current therapeutics target for cancer therapy." (PMID 35578244, 2022). "Since we observed an impact of altered zinc homeostasis upon the surface expression and phosphorylation of the EGFR, we investigated whether the altered zinc homeostasis also affects the expression of the EGFR-regulated, cancer-relevant proteins E-cadherin, MMP-2 and PD-L1." (PMID 35216384, 2022). "Therefore, EGFR inhibitors have been utilized for cancer treatment." (PMID 35223483, 2022). "Targeting this organelle may be a new approach to overcoming EGFR-mediated cancers." (PMID 36438839, 2022).
cancer (continued). "Several therapeutics for cancers throughout the body targeting EGFR and its variants have been developed over the years, including the FDA-approved EGFR tyrosine kinase inhibitors afatinib and dacomitinib, and monoclonal antibodies against EGFR such as cetuximab, panitumumab, and nimotuzumab." (PMID 35890738, 2022). "In addition, IFIT1 and IFIT3 are critical for EGFR recycling and activation in other cancers." (PMID 35280763, 2022). "Therefore, agents targeting EGFR could effectively suppress the growth of these EGFR-addictive cancers." (PMID 35062949, 2022). "In summary, achieving the goal of complete and safe cancer eradication through ICIs may require only monotherapy in a few patients with EGFR-mutant NSCLC, while most of these patients may need combination therapy, and the major challenge for the latter group is joint toxicity." (PMID 35935943, 2022). "Moreover, cancer is a highly heterogeneous disease, and polyclonal cell lines may exist with various EGFR statuses." (PMID 35912248, 2022). "Considering the specificity of cet.Hum.scFv-IRDye800CW toward EGFR-overexpressing cells and also the less tissue penetration ability of infrared wavelengths (compared to X-rays, gamma rays, and so on), it will be useful only for imaging of superficial human cancers that overexpress EGFR." (PMID 35517713, 2022). "Therefore, EGFR is an ideal cancer biomarker for designing EGFR-based targeted therapies." (PMID 36146510, 2022). "Thus, our finding suggested that targeted DDX20 may be a therapeutic strategy for controlling EGFR copy number heterogeneity in cancer." (PMID 36246406, 2022). "Anti-EGFR mAbs, especially those of the IgG1 subclass, may also activate the host immune system (antibody-dependent cellular cytotoxicity and complement-mediated cytotoxicity) to destroy the cancer cell." (PMID 35455247, 2022). "Furthermore, cancer cells with high TRPV4 expression are more sensitive to EGFR-targeted therapy, further suggesting that EGFR and TRPV4 expression may be functionally linked." (PMID 36497413, 2022). "Thus, although cancer patients can be distinguished from healthy donors based on the presence of EpCAM+EGFR+ cells, patients with benign inflammatory colon diseases could be misclassified as cancer patients." (PMID 36613466, 2022). "Indeed, these intriguing findings shed light on the previously unrecognized role of activated autocrine ACh signaling in driving initial cancer therapy escape, which exposes a therapeutic vulnerability that can be clinically exploited to prolong the efficacy of EGFR-TKI treatment." (PMID 36048538, 2022). "Additionally, pemetrexed is approved for patients with non-squamous but not for squamous NSCLC, a population enriched in EGFR mutations compared to the population of cancer patients who qualify for treatment with carboplatin." (PMID 35907849, 2022). "EGFR inhibitors, such as gefitinib, lapatinib and afatinib, have been approved to treat cancers, but severe drug resistance of EGFR inhibitors leads to low clinical response, which may be caused by drug-induced EGFR mutations (e.g. EGFRL858R, EGFRT790M or EGFRC797S)." (PMID 35410300, 2022). "Besides EGFR, there are other RTKs that have been shown to be important targets in cancer." (PMID 36000167, 2022). "Also the in silico studies proved that the docking score of the compound suggests the interaction of the compound which could tightly regulate key target genes controlling cancer like ER, EGFR kinase, EGFR-cSRC, HDAC-2, PARP-1 and BRAF." (PMID 35059624, 2022). "Hence, advances in biomarkers and genomic fields are considered the future of cancer investigation, and EGFR as an important proven marker could be used in this regard." (PMID 35463723, 2022). "However, EGFR-TKIs also decrease PD-L1 expression in cancer cells." (PMID 35742933, 2022). "However, EGFR Q787Q polymorphism is not a somatic mutation in cancer but is rather a germline variant that exists in a section of the non-cancerous population." (PMID 35387120, 2022).
cancer (continued). "Because many protein kinases have been implicated for EGFR signaling pathways, we have carried out Luminex multiplexing assays to screen a set of EGF-associated signaling kinases that are proposed to control glucose metabolism and/or serine biosynthesis in various cancer cells." (PMID 35122791, 2022). "We sought to characterise how AZD0424, and by extension SRC inhibitors in general, may be employed as part of anti‐cancer combination therapy in CRC as AZD0424 treatment could repress transducers of downstream signalling from EGFR, a key driver of metastatic CRC." (PMID 34856074, 2022). "Thus, EGFR is an attractive target for peptide therapeutics against cancers." (PMID 36410436, 2022). "Cancer cells may be sensitized to gefitinib by HDAC inhibitors, an effect that may be associated with the up-regulation of Bim34,35 and the down-regulation of EGFR and c-Met." (PMID 35188360, 2022). "Data suggest that FAM83A may be involved in the EGFR signaling in both normal and cancer cells." (PMID 35183258, 2022). "In addition, Rap1 has been traced to attenuate metastasis and EGFR-triggered carcinoma." (PMID 36686654, 2022). "JAC1 may have equal significance in EGFR positive cancer therapy." (PMID 33875644, 2021). "Furthermore, aberrant EGFR tyrosine kinase activity remains a promising target in cancer therapy." (PMID 33466795, 2021). "Consequently, the inhibition of EGFR or AURKA reverses the adaptation of cancer cells to ARS-1620." (PMID 34607583, 2021). "EGFR is the target of several drug therapies, and the variability of its interactions may account for its ability to circumvent drug-induced inhibition in resistant cancer cells." (PMID 33603128, 2021). "Besides receptor overexpression, cancer cells also exhibit a striking deregulation between the spatial distribution, interaction, and signaling strength of membrane receptors, including EGFR and HER2, which correlates with an increased risk of resistance against targeted therapeutics." (PMID 34831465, 2021). "However, cancer cells inevitably develop acquired resistance (AR) to EGFR-TKIs." (PMID 33953280, 2021). "Thus, after HCC cells were treated by ESO, the downregulated phosphorylation of EGFR may contribute to its anti-cancer effects." (PMID 33746755, 2021). "As cancer cells, trophoblast derived cells express several proto-oncogenes; for example, CTB and STB exclusively express proto-oncogenes that encode Growth Factor Receptor c-erbB1 (Human Epidermal Growth Factor Receptor 1 (HER1), Epidermal Growth Factor Receptor 1 (ERBB1 or EGF-receptor))." (PMID 33937039, 2021). "In addition to the previous parameters, such as the patient’s age, general performance, presence or absence of cancer outside the CNS, the number of brain metastases (one–four or >four), it also takes into account the gene status of the EGFR and ALK mutations." (PMID 33435596, 2021). "Additionally, the direct interaction between HKII and the EGFR/Akt pathway could be essential to modulate cancer progression." (PMID 34887764, 2021). "In addition, sorafenib has been connected with key signalling pathways in cancer such as EGFR/EGF." (PMID 34655447, 2021). "Therefore, novel therapeutics that kill EGFR-expressing cancer cells by an action mechanism different from EGFR inhibitors by suppressing EGFR function may be a potential option for TNBC treatments." (PMID 34879870, 2021). "During EMT and cancer progression, when hemidesmosomes are lost, the cytoplasmic domain of ITGβ4 is phosphorylated, which releases the integrin α6β4 from the hemidesmosomes and freely interacts with different growth factors receptors such as the epidermal growth factor receptor (EGFR)." (PMID 34638469, 2021). "In this regard, our previous data indicated that HBP inhibition, achieved through cancer cell treatment with the FR054, causes the decrease in the integrin membrane localization, cell adhesion, and migration, as well as the inhibition of the EGFR and Akt signaling." (PMID 33670598, 2021).
cancer (continued). "Furthermore, downregulated oncogenes in cluster 1 might be associated with several cancer pathways, such as MAPK, TNFR1-induced NF-κB, and EGFR." (PMID 34571936, 2021). "Finally, we could show that our structure-based screening approach identifies novel repositioning candidates for the cancer target EGFR/HER2." (PMID 34451888, 2021). "In addition, we also found that a set of 730 CpG sites located within the epi-driver genes had the same direction of change for three or more cancer subtypes, including genes that had previously proved to have biological functions in cancer progression such as EGFR, NCOR2, MAML3, TSC2, and FGFR2." (PMID 35069697, 2021). "Additionally, features of stemness accompanied elevated PD-L1 levels in EGFR-positive cancers." (PMID 34680249, 2021). "More importantly, EGFR and PTK2/FAK had the highest AUC value (0.715) among all genes, indicating that EGFR and PTK2/FAK could be suitable biomarker candidates associated with cancer progression." (PMID 33634070, 2021). "Therefore, specific EGFR inhibition is one of the promising methods for cancer therapy." (PMID 34512175, 2021). "Thus, analysis of the inhibitory function of ERp57 on EGFR-mediated cancer could open a new avenue to further explore optimized treatment options." (PMID 33758622, 2021). "Meanwhile, it will be interesting to see whether known transcription factors that regulate AXL synthesis (i.e., activator protein AP1, YAP/TAZ/TEAD, and HIF1α) can mediate the predominant activation AXL and promote EGFR-TKI-specific resistance trajectory in chemoresistant cancer cells." (PMID 33850249, 2021). "From the drug target prediction, GO and pathway enrichment analysis and pharmacology networks analyses, we suggested that the anti-cancer effects of SO on HCC might be related to regulate cancer cell proliferation and survival via pathways including EGFR, PI3K/AKT, NFκB and MAPK signaling pathways." (PMID 33746755, 2021). "The mechanism of its anti-cancer activity has been elucidated by metastasis inhibition, a block of the cell cycle at the G2/M phase, and apoptosis induction, which are commonly known to be disrupted by the epidermal growth factor receptor (EGFR) signaling pathways." (PMID 34201116, 2021). "However, since sorafenib is proved to be an ERK signaling inhibitor and the structure of UC2288 is similar to that of sorafenib, we thus asked whether EGFR/ERK pathway was involved in UC2288 anti-cancer activity." (PMID 33442398, 2021). "Moreover, the broad spectrum of tumors responding to inhaled topotecan may offer additional therapies following progression of EGFR or KRAS mutant cancers." (PMID 33860729, 2021). "Moreover, several studies have been reported that PAR2 could modulate numerous cancer cell functions, such as proliferation, migration and apoptosis, by EGFR transactivation or itself." (PMID 33967759, 2021). "Indeed, it is well known that miR146a is a master controller of EGFR expression in cancer cells." (PMID 34055629, 2021). "In addition to its localization in cancer cells, EGFR can also be found in the kidney." (PMID 34885014, 2021). "Moreover, the AREG/EGFR signaling pathway may be involved in cancer progression through enhanced Treg cell function, leading to the activation of NFκB, which is closely related to neoadjuvant chemotherapy response and survival of patients with EAC." (PMID 34724890, 2021). "Therefore, we conducted a hypothesis that the level of methylation may affect the expression of EGFR inhibitors of responsive genes, and then influence the effectiveness of drugs in cancer." (PMID 34356665, 2021). "Thus, studies should examine how to overcome EGFR-TKI resistance in cancer therapies." (PMID 34884633, 2021). "Additionally, a subpopulation of cancer is primarily resistant to EGFR inhibitors." (PMID 33801379, 2021).
cancer (continued). "Our results also revealed that GE11-CUR/ICG-LPs with NIR irradiation could induce cancer cell apoptosis by promoting ROS generation and cytoskeleton disruption through the activation of apoptotic signaling pathways and the inhibition of EGFR-mediated PI3K/AKT pathway." (PMID 33868396, 2021). "The mode of action of β-blockers in vitro linked to cancer growth inhibition through impaired production of vascular endothelial growth factor (VEGF), decreased cytokine serum levels, and enhanced the effect of epidermal growth factor receptor (EGFR) inhibitors." (PMID 33867973, 2021). "In addition, cellular experiments exhibited EGFR inhibitors might reverse of Warburg effect, one metabolic process of the excessive conversion from glucose to lactate in cancers, and re-activate oxidative phosphorylation of cancer cells for cancer therapy." (PMID 34844602, 2021). "However, cancer cells often become tolerant to EGF/EGFR signaling-targeted therapies." (PMID 32901097, 2021). "For example, Māori may have had a lower proportion of EGFR mutation-positive cancers because of a higher incidence of EGFR mutation-negative disease, a lower incidence of EGFR mutation-positive disease or both." (PMID 33961689, 2021). "Co-culture of EGFR-mutated sensitive cells and EGFR-nonmutated resistant cells promoted osimertinib resistance phenotype in EGFR-mutated cancer cells, while depletion of exosomes from conditioned medium or blockade of exosomal EGFR by neutralizing antibody alleviated this phenotype." (PMID 33461557, 2021). "Cytotoxic anticancer agents attack cancer cells with or without EGFR mutations, and their combination with EGFR-TKIs may prevent the growth of EGFR-TKI-resistant cells." (PMID 34831415, 2021). "Therefore, anti‐EGFR‐based treatments would be therapeutic strategies for cancers." (PMID 33960631, 2021). "However, after long-term exposure, DTCs are hypothesized to be an important source of cancer cells that eventually acquire irreversible resistance mechanisms to EGFR TKIs." (PMID 34202566, 2021). "Thus, GALNT2 may suppress the malignant phenotype of cancer cells by preventing the activation of EGFR and its downstream signaling pathway." (PMID 34069424, 2021). "Although the underlying mechanisms causing this aberrant expression of HER3 in cancer cells, especially following EGFR-targeting treatment, is not fully elucidated, HER3 may be a potential target for anticancer therapy in these resistant cells." (PMID 33801379, 2021). "By combining EGFR, ERBB2, and ERBB3 protein expression in a decision tree model, we identified an association with biochemical recurrence (log rank = 25.295, p < 0.001), development of bone metastases (log rank = 23.228, p < 0.001), and cancer-specific mortality (log rank = 24.586, p < 0.001)." (PMID 33918389, 2021). "We propose that SG apparently enhanced anti-cancer potency of cetuximab may be due to the dual interaction on EGFR contributes to enhanced inhibition of EGFR activation: cetuximab interferes with the tethered (closed) conformation while SG interferes with the un-tethered (extended) conformation." (PMID 33946151, 2021). "Additionally, EGFR is present on the plasma membrane and upon radiation, evades degradation, and translocates to the nucleus and cellular organelles that generate resistance in cancer cells." (PMID 34094980, 2021). "Since lapatinib is an FDA-approved drug for cancer treatment, one might wonder whether the analgesic effects of lapatinib were caused by the inhibition of EGFR/HER2 rather than mPGES-1." (PMID 33574423, 2021). "Thus, aberrant signaling by EGFR drives tumorigenesis and the progression of many cancers." (PMID 34054523, 2021).